PISD (phosphatidylserine decarboxylase)
Description:
Catalyzes the formation of phosphatidylethanolamine (PtdEtn) from phosphatidylserine (PtdSer). Plays a central role in phospholipid metabolism and in the interorganelle trafficking of phosphatidylserine. May be involved in lipid droplet biogenesis at the endoplasmic reticulum membrane (By similarity).
Synonyms: dJ858B16.2; PSDC; DJ858B16; LIBF; PSSC
Tractability: Antibody: UniProt places it where antibodies can reach, with medium confidence; UniProt predicts a signal peptide or a membrane-spanning region. PROTAC: ubiquitination databases record sites on it; its protein half-life has been measured.
Gene: Protein-coding gene on chromosome 22 (31,618,489 to 31,662,239, reverse strand). Ensembl gene ENSG00000241878.
Subcellular location: Mitochondrion inner membrane (Phosphatidylserine decarboxylase beta chain); Mitochondrion inner membrane (Phosphatidylserine decarboxylase alpha chain); Cytoplasm; Mitochondrion inner membrane (Isoform 1); Mitochondrion inner membrane (Isoform 2); Lipid droplet
Subcellular location (Human Protein Atlas): Cytosol; Golgi apparatus
Pathways (Reactome):
Metabolism: Synthesis of PE
Gene Ontology:
Molecular function: phosphatidylserine decarboxylase activity
Biological process: lipid droplet formation; mitochondrial protein catabolic process; phosphatidylethanolamine biosynthetic process; regulation of mitochondrion organization; phospholipid biosynthetic process; protein autoprocessing
Cellular component: cytoplasm; cytosol; lipid droplet; mitochondrial inner membrane; mitochondrion; nucleus
Genetic constraint (gnomAD): Loss-of-function variants: 29 observed, 40.39 expected, observed/expected ratio (o/e) 0.72, 90% interval 0.53 to 0.98. The upper end of that interval is the gene's LOEUF score, 0.98, which puts it in group 4 of 6, group 1 being the genes least tolerant of losing a copy. Missense variants: 494 observed, 529.87 expected, observed/expected ratio (o/e) 0.93, 90% interval 0.87 to 1. Synonymous variants: 249 observed, 224.71 expected, observed/expected ratio (o/e) 1.11, 90% interval 1 to 1.23.
Gene-disease validity (ClinGen):
ClinGen rates the evidence that PISD causes each of these diseases.
Liberfarb syndrome (autosomal recessive): Moderate. A progressive disorder involving connective tissue, bone, retina, ear, and brain, characterized by early-onset retinal degeneration, sensorineural hearing loss, microcephaly, intellectual disability, and skeletal dysplasia with scoliosis and short stature.
Homologues: Orthologues: chimpanzee PISD (99% identical), dog PISD (91% identical), rabbit PISD (88% identical), rat Pisd (85% identical), guinea pig PISD (75% identical), pig PISD (73% identical), mouse Pisd (71% identical), tropical clawed frog pisd (65% identical), zebrafish pisd (61% identical), Drosophila melanogaster Pisd (41% identical), macaque PISD (41% identical), Caenorhabditis elegans psd-1 (32% identical).
Diseases named in the same sentence as PISD in open-access papers:
PISD is named in the same sentence as 21 diseases in open-access papers, as found by Europe PMC text mining. Sharing a sentence is not in itself a finding about the gene and the disease. The quoted sentences say what the papers report.
breast carcinoma (3 papers, 2018 to 2021). "Increasing expression of PISD in breast cancer cells not only reduces primary tumor growth but also causes mitochondrial fragmentation, loss of mitochondrial mass, and perturbations in cellular metabolism." (PMID 29321615, 2018). "We also observed that stable expression of PISD reduced overall movement of breast cancer cells on tissue-engineered constructs with aligned fibrils of fibronectin." (PMID 32503622, 2020). "Data from the TCGA for breast cancer demonstrated higher levels of PISD and Drp1 in patients alive 5 years after initial diagnosis." (PMID 32503622, 2020). "We first analyzed the expression of PISD in primary circulating tumor cells (CTCs) from patients with advanced breast cancer." (PMID 32503622, 2020). "Using an orthotopic xenograft model, we previously showed that overexpression of phosphatidylserine decarboxylase (PISD) in breast cancer cells significantly reduced local tumor growth." (PMID 32503622, 2020). "Compared to the expression of PAI1, a gene known to correlate with worse outcome in patients, or EPCAM, a gene that is commonly overexpressed in breast cancer, breast CTCs expressed low levels of PISD." (PMID 32503622, 2020). "Together, these data establish that increased levels of PISD reduce the ability of breast cancer cells to metastasize." (PMID 32503622, 2020). "We found that PISD is significantly downregulated in migratory cells, and low expression correlates with reduced survival in patients with breast cancer." (PMID 29321615, 2018). "Concordance between decreased levels of PISD in migratory cells and poorer survival supports further analysis of PISD as a potential new regulator of TICs in breast cancer." (PMID 29321615, 2018). "Overall, the results show that PISD regulates several in vitro phenotypes associated with EMT and TICs in breast cancer." (PMID 29321615, 2018). "Data from the TCGA for breast cancer accessed through Oncomine showed a trend toward lower expression of PISD in invasive ductal carcinoma relative to normal breast tissue, although extensive overlap exists." (PMID 29321615, 2018). "For the first time, this research establishes PISD as novel regulator of TICs in breast cancer and highlights mitochondrial functions and dynamics as potential therapeutic targets specifically against TICs." (PMID 29321615, 2018). "PISD converts phosphatidylserine (PS) to phosphatidylethanolamine (PE) in mitochondria, so we expected stable overexpression of this enzyme to elevate amounts of PE in breast cancer cells." (PMID 32503622, 2020). "Among candidate genes, we validated phosphatidylserine decarboxylase (PISD), a gene highly downregulated in migratory cells, as a novel regulator of TIC cells in breast cancer." (PMID 29321615, 2018).
Liberfarb syndrome (2 papers, 2021 to 2022). "Additionally, variations in the PISD gene, which codes for the PS decarboxylase enzyme (PSD) have been connected to a novel mitochondrial disease named Liberfarb syndrome (OMIM #618889–Liberfarb syndrome; LIBF)." (PMID 36687696, 2022).
breast tumor (1 paper, 2020). "Building on our previous discovery that PISD drives mitochondrial fission and inhibits breast tumor growth, we establish that PISD also inhibits metastasis and bone destruction." (PMID 32503622, 2020).
gastric cancer (1 paper, 2026). A primary or metastatic malignant neoplasm involving the stomach. "Collectively, our findings reveal a previously unrecognized role of PISD in linking mitochondrial phospholipid metabolism to STAT3/GPX4-dependent ferroptosis, providing mechanistic insights into the regulation of ferroptosis in gastric cancer." (PMID 41899452, 2026).
glioblastoma (1 paper, 2023). The most malignant astrocytic tumor (WHO grade IV). "According to the GEPIA platform, the expression of PISD, ECT/PCYT2, and SELENOI does not differ between glioblastoma tumor tissue and healthy brain tissue." (PMID 37046844, 2023).
lipid metabolism disorders (1 paper, 2023). "To further understand the mechanism of liver lipid metabolism disorders in T2DM, we tested the mRNA and protein levels of PCYT2 and PISD in L02 cells under HG&FFA stimulation." (PMID 36716821, 2023).
melanoma (1 paper, 2025). A malignant, usually aggressive tumor composed of atypical, neoplastic melanocytes. "In melanoma, low expression of PISD was more favorable for survival, while in pancreatic cancer high expression of PISD was more favorable for survival, suggesting that PISD may have a different role depending on the cancer type." (PMID 40709271, 2025).
Obesity (1 paper, 2025). Accumulation of substantial excess body fat. "EGCG prevents obesity-induced precocious puberty by reshaping lipid metabolism, with key enzymes (PISD, PLD, and PTDSS) in glycerophospholipid metabolism serving as potential therapeutic targets." (PMID 41280390, 2025). "Taken together, these findings suggested that EGCG exerts its preventive effect on obesity-induced precocious puberty via high-affinity binding to key lipid-metabolizing enzymes (PISD, PLD, and PTDSS) and subsequent regulation of glycerophospholipid homeostasis." (PMID 41280390, 2025). "In conclusion, EGCG may restore lipid metabolic homeostasis by targeting key nodes—PISD, PLD, and PTDSS—in glycerophospholipid metabolism, thereby ameliorating lipid disorders and contributing to the prevention of obesity-induced precocious puberty." (PMID 41280390, 2025).
retinal degeneration (1 paper, 2024). Degeneration of the retina. "Moreover, overexpression of PISD prevented rhabdomere loss and retinal degeneration seen in aged slmoRNAi5-expressing flies." (PMID 39680501, 2024). "We previously demonstrated that overexpression of PISD in pect mutant flies increases the synthesis of PE in mitochondria, restores overall cellular PE homeostasis, and rescues retinal degeneration and defective visual responses." (PMID 39680501, 2024).
tumor (12 papers, 2018 to 2026). "In vivo, PISD downregulation is significantly accompanied by a reduction in tumor growth in GC xenograft models." (PMID 41899452, 2026). "LACTB inhibits phosphatidylserine decarboxylase and reduces the abundance of phosphatidylethanolamine and lyso-phosphatidylethanolamine, leading to a mitochondrial state compatible with tumor suppression, decreased proliferation, and enhanced differentiation." (PMID 36078157, 2022). "The physiological significance of PISD has been demonstrated in tumor-initiating cells, where overexpression of PISD downregulates mitochondrial function and inhibits tumor growth." (PMID 33707636, 2021). "To verify that stable expression of PISD elevates amounts of PE in vivo, we analyzed orthotopic tumor xenografts of PISD and WT cells by MALDI imaging mass spectrometry." (PMID 32503622, 2020). "Our previous work suggests that PISD inhibits tumor growth and metastasis by inducing mitochondrial fission." (PMID 32503622, 2020). "In the current study, we identified that knockdown of TFAM repressed the synthesis of autophagy bio-marker LC3-II in tumor cells and decreased the expression of phosphatidyl-serine decarboxylase (PISD)." (PMID 32093281, 2020). "Overexpression of PISD significantly reduced orthotopic tumor growth as quantified by imaging over 40 days." (PMID 29321615, 2018). "Concordant with these findings, PISD overexpression significantly reduced growth of orthotopic tumor xenografts in mice." (PMID 29321615, 2018). "Moreover, LACTB, a tumor suppressor gene, is downregulated in many tumor cell lines and has been found to downregulate PISD." (PMID 36716821, 2023). "In this study, a hypothesis was presented according to which the tumour suppressive effect of an increased LACTB level is mediated by a decreased activity of the mitochondrial enzyme phosphatidylserine decarboxylase (PISD)." (PMID 35626737, 2022). "PISD also reduced the formation of tumor-spheres from single cells in only SUM159 cells." (PMID 29321615, 2018). "Based on these results, we concluded that PISD was key for autophagy flux in tumor cells, and its downregulation in TFAM knockdown tumor cells resulted in the inhibition of autophagy." (PMID 32093281, 2020). "To investigate PISD in tumor formation, we injected 2 × 104 SUM159-PISD-mCherry or control mCherry cells orthotopically into the mammary fat pads of female NSG mice." (PMID 29321615, 2018). "Notably, recent studies demonstrated an emerging role of PISD in tumor regulation, where the tumor repressor LACTB downregulates PISD levels, leading to the alteration of mitochondrial lipid metabolism and differentiation of certain cancer cells." (PMID 33707636, 2021).
cancer (10 papers, 2016 to 2025). A tumor composed of atypical neoplastic, often pleomorphic cells that invade other tissues. "Taken together, PISD deficiency may alter mitochondrial bioenergetics and cell proliferation differentially depending on cancer type, while the role of mitochondrial PE in HCC metabolism remains unknown." (PMID 40709271, 2025). "As the role of PISD in cancer processes is not well understood, the anticancer potential of inhibitors targeting this enzyme remains uncertain." (PMID 39409074, 2024). "PISD regulated multiple aspects of mitochondria, highlighting mitochondrial functions as therapeutic targets against cancer stem cells." (PMID 29321615, 2018). "A previous study demonstrated in Chinese Hamster Ovary cells that silencing PISD results in severe mitochondrial defects and reduces the cell growth rate, suggesting that PISD may be a promising target for slowing cancer cell progression." (PMID 40709271, 2025). "Moreover, studies on LACTB in cancer revealed that LACTB expression and its enzymatic activity effectively suppress PISD protein levels, thereby limiting the excessive synthesis and accumulation of PE in cancer cell mitochondria." (PMID 39941048, 2025).
infection (2 papers, 2023 to 2024). The state of being infected such as from the introduction of a foreign agent such as serum, vaccine, antigenic substance or organism. "The roles of Bcsdr2 in biofilms and pathogenicity were also supported by quantitative real-time RT-PCR results showing that phosphatidylserine decarboxylase synthesis gene Bcpsd and chitin synthase gene BcCHSVII were downregulated in the early stages of infection for the ΔBcsdr2 strain." (PMID 38940906, 2024).
mitochondrial disease (2 papers, 2019 to 2024). "Very recently, it was reported that treatment of PISD patients, a mitochondrial disease gene encoding phosphatidylserine decarboxylase proenzyme, causing skeletal dysplasia, with lyso-PE allowed to restore mitochondrial morphology." (PMID 31530825, 2019). "Human mutation in the PISD gene, which encodes for the PISD enzyme, causes mitochondrial disease." (PMID 38652544, 2024).
PISD also shares sentences with these, for which no sentence is quoted: congenital cataracts (1 paper); hyperlipidemia (1); Intellectual disability (1); invasive ductal carcinoma (1); liver (1); muscle atrophy (1); pancreatic cancer (1); skeletal dysplasia (1).